ERCC1 (ERCC excision repair 1, endonuclease non-catalytic subunit)
Diseases named in the same sentence as ERCC1 in open-access papers (continued):
Sharing a sentence is not in itself a finding about the gene and the disease.
tumor (continued). "Our study suggests that ERCC1 expression can influence the tumor response and overall survival in NSCLC patients." (PMID 25674147, 2014). "Single gene analysis indicated that ERCC1 and TYMS expression levels were associated with the depth of tumor invasion, while TUBB3 expression was associated with the lymphatic metastasis of ESCC." (PMID 24926347, 2014). "One hundred eight patients were included in the study, and tumor biopsy was collected for genotyping and immunohistochemical analysis of ERCC1." (PMID 25191856, 2014). "The related agent 5-azacytidine augmented expression of the DNA repair enzyme ERCC1 by reducing its promoter methylation, and thereby decreased tumor cell sensitivity to radiation." (PMID 24401732, 2014). "It should be noted that similar staining intensities were observed in both the 19 tumor fixation material and the training study, suggesting limited exogenous influence on ERCC1 expression." (PMID 24603753, 2014). "In a random sample of 18 tumor specimens, we compared the immunohistochemical reaction products to 8 F1 (ERCC1), FL-297 (ERCC1), and to the XPF antibody SPM228, the partner of ERCC1 in dimer formation." (PMID 24817012, 2014). "By chi-square test, we found that patients with low ERCC1 expression showed a significantly higher rate of good tumor response, and the adjusted OR (95% CI) was 2.16(1.32-3.45) (Table-II)." (PMID 25674147, 2014). "The results indicated that the expression of ERCC1 positively correlated with the severity of tumor invasion (r=0.47, P=0.0102)." (PMID 24926347, 2014). "In accordance, our experimental findings in Detroit 562 HNSCC tumor cells also showed that ERCC1 gene expression at the mRNA and protein levels decreased under hypoxia, and even a subsequent normoxic condition did not recover the gene expression changes." (PMID 24817012, 2014). "Unexpectedly, 106 HNSCC patients treated with primary concomitant radiochemotherapy responded better, if ERCC1 expression in pretherapeutic tumor samples was high." (PMID 24817012, 2014). "Patients with limited stage, whose tumours expressed high ERCC1 (p=0.028), PKM2 (p=0.046), TOPOI (p=0.008), TOPOIIA (p=0.002) and TOPOIIB (p<0.001) mRNA had a shorter Progression Free Survival (PFS)." (PMID 24058603, 2013). "Analysis of the 152 tumor specimens with ERCC1-19q13/CEN-2 revealed the presence of both gene deletions and gene gains." (PMID 24144331, 2013). "It is possible that the presence of ERCC1 reflects an inherent biologic characteristic of the tumor." (PMID 23759026, 2013). "EGFR mutation status was determined using the peptide nucleic acid-locked nucleic acid polymerase chain reaction clamp method, and immunohistochemistry was used to examine the expression of ERCC1 in tumor samples obtained from the patients." (PMID 23940741, 2013). "The ERCC1 protein is major component of the NER complex, acting as the rate-limiting enzyme in the NER pathway, while high expression of ERCC1 has been demonstrated to be correlated with poor responses to chemotherapy in various tumor types." (PMID 23426424, 2013). "Adequate tumor specimens were available from 51 of these patients, and were subjected to ERCC1 detection." (PMID 23940741, 2013). "Immunohistochemical staining for TUBB3 and ERCC1 was performed using paraffin wax-embedded tumor tissues." (PMID 24053422, 2013).
tumor (continued). "The primary objective was to assess the objective response rate (ORR), while EGFR and KRAS mutations and mRNA and protein expression levels of ERCC1 and RRM1 were analyzed in tumor tissues and blood samples." (PMID 23621919, 2013). "The immunostaining patterns for TUBB3 were cytoplasmic, whereas the ERCC1 expression patterns in the tumor cells were nuclear The expression status of TUBB3 and ERCC1 did not correlate with each other (P = 0.245)." (PMID 24053422, 2013). "The positive rate of ERCC1 mRNA in tumor and its adjacent tissues were 58.8% and 55.9% respectively (P = 0.769)." (PMID 22439756, 2012). "ERCC1 mRNA expression was determined by quantitative real-time RT-PCR in pre-treatment tumor tissues." (PMID 23259415, 2012). "Accordingly, Ercc1 activity levels have been viewed as a potentially important prognostic biomarker for tumor responsiveness to cisplastin." (PMID 23095216, 2012). "Five studies were available in regard SCLC patients receiving platinum-based chemotherapy, contributing data on 292 patients, of whom 92 (32%) had high ERCC1 expressing tumours." (PMID 22022380, 2011). "Seven datasets assessing 896 patients, with high ERCC1 expression observed in 48% of tumours, were available for pooling estimates of survival in patients who underwent surgery alone without systemic therapy." (PMID 22022380, 2011). "Six studies assessed ERCC1 in tumours from unselected patients enrolled into clinical trials, whilst in the remainder patients were not accrued to a trial." (PMID 22022380, 2011). "Tumour response stratified by ERCC1 expression was reported by ten NSCLC data-sets comprising 656 patients, 328 (50%) of whom had high expression." (PMID 22022380, 2011). "OS HR estimates obtained from 1,391 NSCLC patients who received platinum were available for meta-analysis, 640 (46%) of whom had tumours with high ERCC1 expression." (PMID 22022380, 2011). "Several studies in the preclinical, adjuvant and palliative setting have been performed, using 2 main laboratory approaches: First, patient tumor tissue was examined for ERCC1 expression by either RT-PCR (mRNA) or IHC (protein)." (PMID 21961533, 2011). "Elevated ERCC1 mRNA expression has previously been shown to predict resistance to chemotherapy in gastro-oesopahgeal tumours." (PMID 20461087, 2010). "We provide evidence that tumour regression and ERCC1 nuclear protein expression evaluated by immunohistochemistry are promising predictive markers in gastro-oesophageal cancer patients receiving neoadjuvant platinum-based chemotherapy." (PMID 20461087, 2010). "Gomez-Roca and colleagues (2009) assessed the levels of ERCC1 in primary NSCLC tumor specimens compared with the levels found in corresponding metastases." (PMID 21152077, 2010). "The antibody 8F1 (Neomarkers; Fremont, CA), which recognizes the ERCC1 protein, is used to assess ERCC1 levels within tumor cells present in tissue sections obtained from lung biopsy or tumor resection." (PMID 21152077, 2010). "Results were dichotomized into negative and positive based on a cutoff of 10% ERCC1 antibody reactivity within tumor cells (i.e., a positive result indicated that at least 10% of cells demonstrated a reactivity to the ERCC1 antibody)." (PMID 21152077, 2010). "Germline heterozygocity was replaced in one case by homozygocity for the rare A/A allele for ERCC1 C8092A/CD3EAP Q504K, indicating a Lys/Lys genotype for CD3EAP in the tumor." (PMID 20066159, 2009). "Several groups have reported that mCRC patients with the ERCC1-118 TT or CT genotype had better tumour response or survival compared with CC patients." (PMID 19672255, 2009). "In this context, our findings provide additive evidence that the pretreatment level of ERCC1 in tumour cells is negatively related to the treatment outcome of platinum compounds." (PMID 18594541, 2008). "Subjects whose metastatic tumor tissue had ERCC1 mRNA expression greater than the 3rd quartile had a shorter median time to treatment failure (12 vs 23 weeks)." (PMID 19105824, 2008).
tumor (continued). "Nevertheless, important issues regarding standardization and optimization of technical procedures for ERCC1 analysis in tumor samples remain to be resolved before this methodology can be implemented in daily clinical practice." (PMID 19578506, 2008). "ERCC1 immunohistochemical expression in the tumour samples was dichotomized to either “high” or “low”, using the median value of ERCC1 expression as the “cut off” value." (PMID 19578506, 2008). "A correlation between increased ERCC1 expression with resistance to cisplatin or with poor survival has been reported for several tumours including SCCHN." (PMID 18594541, 2008). "ERCC1 and TS levels were detected in all tumours, with median gene expression relative to housekeeping β-actin for ERCC1 of 0.039 (range 0.001–5.23, 95% confidence interval (CI): 0.26–0.83) and for TS of 8.83 (range 0.72–78.79, 95% CI: 8.03–12.34)." (PMID 18362936, 2008). "The univariate analysis revealed that tumour stage, tumour location, and ERCC1 expression were important factors affecting the prolongation of both PFS and OS." (PMID 18594541, 2008). "Seven hundred and sixty one tumor specimens were analyzed to evaluate the expression of ERCC-1 protein by immunohistochemistry (IHC)." (PMID 19452042, 2008). "This study showed for the first time that assessment of ERCC1 mRNA expression in tumour tissue is feasible in the clinical setting in order to predict response to platinum-based chemotherapy." (PMID 19578506, 2008). "We observed a significant increase in ERCC1 levels in both tumor-derived breast (p = 0.0266, Wilcoxon matched pairs test) and ovarian cells (p = 0.0156, Wilcoxon matched pairs test)." (PMID 16026610, 2005). "The high expression of ERCC1 protein may be the main mechanism of drug resistance to platinum-based chemotherapy in tumor patients." (PMID 38819674, 2024). "Of note, even though elevated ERCC1 levels are associated with resistance to platinum agents due to increased ICL repair, trial patients with high ERCC1 expression in their tumours derived the most clinical benefit from the addition of pevonedistat to carboplatin and paclitaxel." (PMID 37226898, 2023). "In other words, a higher expression of ERCC1 may indicate a potential failure in chemotherapy due to the efficient repair of genetic damage in tumour cells induced by platinum analogues." (PMID 36181289, 2022). "Furthermore, the mRNA and protein expression of ERCC1 in tumour tissues were compared between the AA and CC genotypes of rs3212986." (PMID 36181289, 2022). "Next, we performed an immune analysis to understand the role of ERCC1 expression in tumor immunity." (PMID 36338712, 2022). "ERCC1 has been found to be involved in drug resistance in a variety of tumor tissues." (PMID 35674307, 2022). "Tumour expression of TOP2A, RRM1, HER2 and ERCC1 may associated with the sensitivity of NMIBC to pirarubicin or gemcitabine treatment." (PMID 35711974, 2022). "Consistent with previous reports, whether the high expression of ERCC1 mRNA or protein was positively correlated with the resistance of tumour cells to CDDP." (PMID 36181289, 2022). "ERCC1 is a potential tumor marker that may interact with other clinical indicators and affect the prognosis of patients." (PMID 36338712, 2022). "With respect to ERCC1 gene, the higher intensity was significantly related to T1 tumor (mean rank: 64.79 > 42.26, p < 0.001), ER-positive (mean rank: 54.98 > 37.41, p = 0.002), PR-positive (mean rank: 58.35 > 39.05, p < 0.001) and Ki-67 < 20% (mean rank: 66.00 > 44.30, p = 0.001)." (PMID 35204496, 2022). "Inhibition of ERCC1 expression correlated positively with DNA repair capacity, thus, miR-149 and ERCC1 may represent a target to increase the sensitivity of tumor cells to cisplatin." (PMID 33867871, 2021).
tumor (continued). "In 1 of 39 tumor types, PD‐L1 expression and ERCC1 negative were associated; hence, combinations of platinum and immunotherapy are likely beneficial in this tumor type." (PMID 31479512, 2020). "For ERCC1, the Fisher's exact test was significant in 4 of 40 tumor types." (PMID 31479512, 2020). "Therefore, in drug-resistant tumor cells, the expression of ERCC1 will be increased, which can repair the genes of tumor cells destroyed during chemotherapy and produce drug resistance of tumor cells." (PMID 32792861, 2020). "Our results show that ERCC1 is increased in the tumor tissue of OSCC patients." (PMID 33029487, 2020). "Hence, a more specific antibody targeting this isoform is required to revalidate the correlation between tumor ERCC1 protein levels and cisplatin effectiveness." (PMID 33291532, 2020). "To clarify these unexpected results, we asked whether the ERCC1/XPF foci number per nucleus could be affected in tumor cells by DDP treatment." (PMID 32847049, 2020). "In 2006, Olaussen first reported that among the patients with NSCLC complete resection, those with low expression of ERCC1 in tumor specimens had a poor prognosis, but could benefit from chemotherapy containing cisplatin." (PMID 32419821, 2020). "The mechanism by which ERCC1 contributes to cisplatin resistance involves a nucleoside excision repair, which removes platinum-DNA adducts and repairs the DNA double-strand breaks, and other reports mention an inherent biologic characteristic of the tumor." (PMID 32167697, 2020). "Indeed, the expression of XPA and components of the ERCC1-XPF nuclease have been found to be lower in cell lines derived from GCTs compared to those from other tumour types." (PMID 31906898, 2020). "The results of the existing literature indicate that platinum drugs and mitomycin sensitivity are associated with tumor ERCC1 expression, gemcitabine sensitivity and negative RRM1 expression." (PMID 33028224, 2020). "However, gender, primary tumour location, and the XRCC1-rs25487, ERCC1-rs11615, ERCC2-rs238406, and ERCC2-rs13181 polymorphisms were not statistically associated with 5-year OS (p’s > 0.05)." (PMID 32397974, 2020). "Cisplatin resistance can emerge even from a small population of ERCC1 high-expressing tumor cells." (PMID 33266377, 2020). "Therefore, when ERCC1 expression gets higher, tumor grows slower, but the benefit of cisplatin treatment is smaller as well." (PMID 31331301, 2019). "More valid method for ERCC1 analysis is RT-PCR for detection of the mRNA from tumor tissue." (PMID 31521181, 2019). "Many single nucleotide polymorphisms have been identified in ERCC1 and ERCC2 genes; of these polymorphisms, ERCC1 (C118T & C8092A) and ERCC2 (A751C & G312A) have been shown to affect the repair capacity and concomitantly the tumor’s sensitivity to cisplatin." (PMID 29980176, 2018). "However, if an oncologist was inclined to prescribe a combination of cisplatin + fluorouracil, it would be prudent to stain two formalin-fixed paraffin embedded sections for TS and ERCC1 to observe if the tumor possesses resistance markers for these drugs." (PMID 28421164, 2017). "Immunohistochemistry was used to evaluate Ki67 and ERCC1 protein levels in tumor tissues." (PMID 29179456, 2017). "Thus, pretreatment ERCC1 expression status can be used to predict tumor response and survival of patients with recurrent or metastatic uterine cervical cancer receiving platinum-based chemotherapy." (PMID 29390553, 2017). "For these entities it has been proposed that ERCC1 overexpression may serve as a prognostic and/or predictive tumor marker." (PMID 28747165, 2017). "In comparison with poorly differentiated EPNEC, the subgroup of patients with well-differentiated tumours presented comparable frequencies of ERCC1, Bcl-2, and Lin28 IHC expression, similar RR (p = 0.94), but higher Ki-67 index (p = 0.048) and numerically longer OS (p = 0.23)." (PMID 28955403, 2017).
tumor (continued). "In addition, 72 % of the residual cells were characterized as ERCC1-positive, indicating therapy-resistant tumor cell populations." (PMID 26868521, 2016). "A small study using IHC for ERCC1 assessment suggested that there might be a discrepancy in classifying patients' ERCC1 expression levels depending on whether tumour tissue was obtained using biopsy or surgical resection." (PMID 26775588, 2016). "Western blotting assay were used to measure the expression of ERCC1/TOP2A in tumor tissues." (PMID 27895586, 2016). "Additionally, we confirmed the expression of Rad51 and ERCC1 by immunoblotting tumor samples from the in vivo study." (PMID 26599019, 2015). "Next, we evaluated whether metformin affected DNA repair pathways in vivo by immunohistochemically examining the expression of Rad51 and ERCC1 in tumor samples." (PMID 26599019, 2015). "After accounting for the covariates age, sex, tumor grade and ECOG performance status in a Cox proportional hazard model the association of low ERCC1 with longer OS (HR 0.18, 95% CI 0.14 to 0.26, p = 0.0448) and TTF (HR 0.16, 95% CI 0.14 to 0.21, p = 0.0053) remained significant." (PMID 26083491, 2015). "In all of them, Ercc1-siRNA #3 was highly effective in inhibiting tumor growth." (PMID 26336131, 2015). "Indeed, by immunostaining, we are recognizing gene expression and protein synthesis, which reflect regulatory conditions in the tumor tissue, and the ERCC1 level is an indicator of these conditions." (PMID 24817012, 2014). "Therefore, the association between ERCC1, TYMS, RRM1, TUBB3 and TOP2A expression levels with the pathogenesis and development of ESCC was investigated using a clustered analysis in terms of tumor invasion and lymphatic and distal metastasis." (PMID 24926347, 2014). "ERCC1 mediates DNA repair by removing therapeutic adducts from tumor DNA." (PMID 24817012, 2014). "Particularly, tumor specimens of treatment failures revealed significantly lower ERCC1 expression (staining index 28 ± 30 %; mean ± SD) than specimens from controls (58 ± 40 %; p = 0.0064), while specimens from treatment responders (48 ± 35 %) did not (p > 0.05)." (PMID 24817012, 2014). "Elevated ERCC1 expression in tumours, shown here in A549s in comparison to PC9s, is known to mediate resistance to platinum therapy and may account for the absence of an apoptotic response measured here in A549s both in vitro and in vivo." (PMID 24618809, 2014). "The TS and ERCC1 mRNA levels in primary tumor were measured by real-time RT-PCR." (PMID 25175730, 2014). "Tumor samples from fifty-six patients (52%) were identified as ERCC1-positive with an H-score ≥2.0." (PMID 25191856, 2014). "A test of interaction between the prognostic effect of higher ERCC1-19q13/CEN-2 ratios tumor localization approached significance (p = 0.07 with TTR as endpoint), and therefore the multivariate analysis (adjusting for age and gender) was performed separately for each localization." (PMID 24144331, 2013). "When applying relevant ratio cut-off values, tumor specimens could be separated into three different ERCC1-19q13 statuses." (PMID 24144331, 2013). "Recent studies have investigated a number of tumor biomarkers for prognostic and predictive utility when considering systemic therapy and the most prominent amongst these is the excision repair cross-complementation group 1 (ERCC1) protein." (PMID 23759026, 2013).